HOXA9 (homeobox A9)
Diseases named in the same sentence as HOXA9 in open-access papers (continued):
Sharing a sentence is not in itself a finding about the gene and the disease.
tumor (151 papers, 2007 to 2026). "In bladder cancer, tumor-suppressor genes such as RASSF1A, RUNX3, CDH13, and HOXA9 have been reported to undergo promoter hypermethylation, resulting in loss of tumor-inhibitory function." (PMID 41377897, 2025). "While direct evidence in NSCLC is limited, the potential for epigenetically silenced HOXA9 to disrupt these regulatory networks highlights a plausible mechanism underlying tumor progression." (PMID 40699796, 2025). "In this study, HOXA9 staining of PDAC cases showed significant associations with poor prognostic indicators including larger tumor size, higher grade and advanced stage." (PMID 39462379, 2024). "HOXA9 staining of PDAC cases showed significant associations with poor prognostic indicators including larger tumor size, higher grade and advanced stage." (PMID 39462379, 2024). "High H score values of HOXA9 staining showed significant associations with larger tumor size (p < 0.001), higher histological grade (p < 0.005), T2 tumor stage (p < 0.002) and advanced stage group (p < 0.001)." (PMID 39462379, 2024). "This study evaluated the correlation between HOXA9 and tumor-infiltrating molecules and discussed its association with therapeutically approved antineoplastic drugs." (PMID 38904676, 2024). "Recent studies have found that the HOXA9 gene encodes an important transcriptional regulator in embryonic development, hematopoietic regulation, and tumor development." (PMID 35783150, 2022). "The in vivo experiment showed that BMPER was highly expressed in the early tumor growth phase (20 days), CXCL10 and HOXA9 expression was elevated with tumor progress, and spatially associated with tumor vasculature." (PMID 32432046, 2020). "In NSCLCs, however, HOXA9 has been implicated in the inhibition of tumor progression and metastasis." (PMID 33238593, 2020). "In clinical settings, lower expression of HOXA9 is greatly associated with elevated tumor invasion, metastasis, and patient mortality." (PMID 31013831, 2019). "HOXA9-overexpression augmented the expression of genes associated with increased stem-cell characteristics, invasion, migration, and tumor vasculature, among other cancer hallmarks." (PMID 26484224, 2015). "Cluster II contained genes associated with tumor progression and metastasis, including HOXA9, MUC13, and members of the GAGE and CT-45 families." (PMID 21333016, 2011). "HOXA9 hypermethylation was associated with advanced tumor stage (stages II and III)." (PMID 40699796, 2025). "HOXA9 might attract CD163 expressed tumor associated macrophages (TAM) and could affect PDAC prognosis." (PMID 39462379, 2024). "In conclusion, HOXA9 could potentiate PDAC progression by stimulating CD163 expressed tumor associated macrophages attraction in tumors." (PMID 39462379, 2024). "Moreover, HOXA9 downregulation is associated with elevated tumor invasion, metastasis, and patient mortality." (PMID 35846378, 2022). "This suggests that HOXA9 could be linked to the calcification and tumour invasion of PTC, which is both independent and dependent of RUNX2." (PMID 31043660, 2019). "Together, these data suggest the HOXA9-mediated genetic signatures in GBM cell models are associated with important cancer hallmarks that may favor tumor development, progression, and aggressiveness." (PMID 25762636, 2015). "Additionally, HOXA9 promoted the malignant transformation of human immortalized astrocytes in an orthotopic in vivo model, and caused tumor-associated death." (PMID 25762636, 2015). "In addition, loss of HOXA5 and HOXA9 expression is generally associated with an increased resistance to apoptosis and tumour survival, although both of these genes are expressed at relatively high levels in SK-OV3 compared to normal ovarian tissue and OV-90." (PMID 20219106, 2010).
tumor (continued). "Moreover, the oncogenic value of CDH3 is reinforced by the upregulation of CDH3‐positively correlated genes upon knockdown of RB and PTEN tumor‐suppressor genes, and by the association with HOXA9, a transcription factor with critical oncogenic functions in GBM." (PMID 34919784, 2022). "A substantial reduction in tumor volume and diminished lung metastasis was observed in nude mice receiving HOXA9-knockdown cells." (PMID 41904140, 2026). "SOX1 and HOXA9 promoter methylation levels were significantly higher in tumor tissues compared to normal lung tissues and blood samples." (PMID 40699796, 2025). "The elevated methylation levels of SOX1 and HOXA9 in tumor samples compared to normal lung tissue and blood samples indicate that these epigenetic alterations are specific to NSCLC." (PMID 40699796, 2025). "This study analyzed the methylation status of SOX1 and HOXA9 in 63 primary NSCLC tumor samples, corresponding normal lung tissues, and circulating blood, using bisulfite pyrosequencing." (PMID 40699796, 2025). "The pluripotency of cancer stem cells, crucial for tumor persistence and recurrence, is strongly linked to the SOX2 (SRY-Box Transcription Factor 2) and HOXA9 (Homeobox A9) TF families." (PMID 41155227, 2025). "In contrast, HOXA9 mRNA expression was elevated in tumor tissues compared to matched normal tissues (1.14 ± 0.1, both n = 10)." (PMID 38285101, 2024). "In summary, our study clarified the effect of HOXA9 on the tumor immune response across various cancer types." (PMID 38904676, 2024). "CAF-conditioned medium induces HOXA9 expression in epithelial ovarian cancer cells, leading to tumor-derived TGF-β2 induction and differentiation of MSCs into CAFs, promoting tumor growth." (PMID 39451251, 2024). "Selected 98 PDAC and 98 adjacent non tumor tissues as a control group were immunostained with HOXA9 and CD163 antibodies." (PMID 39462379, 2024). "In summary, our analysis demonstrates that miR-140-3p is downregulated, while HOXA9 is upregulated in tumor tissues compared to normal tissues, indicating an unfavorable prognosis." (PMID 38285101, 2024). "Taken together, HOXA9 switches between these differential functions and mediates oncogenesis or tumor suppression." (PMID 39462379, 2024). "Conversely, decreased expression of HOXA9 increases glycolysis, while inhibition of HOXA9 by onco-miR-365 acts as a tumor suppressor by obstructing HIF-1α and its glycolytic regulators." (PMID 39637238, 2024). "We evaluated natural killer cell activity (NKA) and methylated HOXA9 circulating tumor DNA (ctDNA) as prognostic biomarkers in NSCLC patients treated with PD-1/PD-L1 inhibitors." (PMID 37137997, 2023). "The most investigated genes were RASSF1A, BRCA1, OPCML, APC, HIC1, and HOXA9, all being tumor-suppressor genes." (PMID 36788585, 2023). "HOXA9 has dual effects (procancer or anticancer) by participating in the proliferation, apoptosis, or differentiation process of tumor cells in different tumor types or at different stages of tumor." (PMID 35111226, 2022). "Methylated homeobox A9 (meth-HOXA9) is tumor specific and has been suggested as a prognostic biomarker in several types of cancer." (PMID 36230519, 2022). "qRT‐PCR verified that HOXA9 was highly expressed in LSCC tissues compared with non‐tumour tissues in 86 pairs of LSCC sample cohort, and its expression was positively correlated with the expression level of KCNQ1OT1." (PMID 34850551, 2022). "What’s should be noted that HOXA9 not only acts a role of oncogene but also a tumor suppressor gene." (PMID 36376832, 2022). "Immunohistochemical analysis showed that the expression of HOXA9 in the tumor tissues of nude mice significantly decreased after ST8SIA6-AS1 knockdown." (PMID 35783150, 2022). "Correlation test results of coexpression of HOXA9 and tumor-related transcription factors showed that HOXA9 was copositively correlated with Twist1." (PMID 35783150, 2022).
tumor (continued). "Further test results showed that ST8SIA6-AS1 knockdown upregulated the expression of miR-5195-3p in tumor tissues while downregulated the expression of HOXA9." (PMID 35783150, 2022). "To evaluate the histologic location and expression of HOXA9 protein in normal and tumor colon tissue, we conducted immunohistochemistry (IHC) staining on normal and tumor tissues from CRC patients." (PMID 35743243, 2022). "Overexpression of miR-365 inhibits expression of the negative regulator of HIF1-alpha, HOXA9, which functions as a tumor suppressor in human cSCCs." (PMID 35408839, 2022). "The methylation level in the methylated EOC tumor samples ranged from 4 to 97% for HOXA9; 7–89% for HIC1; 4–97% for SOX1; 4–95% for DAPK1; 5–97% for SFRP1; 6–99% for SPARC and 4–98% for RASSF1A gene, respectively." (PMID 34778370, 2021). "The relationships between BMPER, CXCL10, and HOXA9 expression and the tumor blood vessels were determined in the early- (20, 30, and 40 days) and late-tumor growth stages (80 days)." (PMID 32432046, 2020). "Of these, BMPER mainly played a role in the early-growth phase of tumors, while CXCL10 and HOXA9 mainly played roles in tumor progression." (PMID 32432046, 2020). "The meth-HOXA9 analysis was based on bisulfite-converted DNA from tumor and plasma and quantified by ddPCR." (PMID 33322500, 2020). "In conclusion BMPER, CXCL10, and HOXA9 promote early tumor growth and progression by stimulating neovascularization of primary HGG." (PMID 32432046, 2020). "The mir-210, a hypoxia-inducible miRNA, inhibits tumor growth of PaC by targeting Hoxa1, Fgfrl1, and Hoxa9." (PMID 33402862, 2020). "CRISPR-mediated deletion of the core sequence CTCF-binding motif in CBS7/9 significantly decreased HOXA9 expression and tumor progression." (PMID 33001025, 2020). "In vitro inhibition of BMPER, CXCL10, or HOXA9 expression reduced the ability of tumor cells to form tube like structure." (PMID 32432046, 2020). "Our research group has previously reported that HOXA9 overexpression inhibits tumor aggressiveness in NSCLC cells." (PMID 33238593, 2020). "The analyses from tumor DNA detected both meth-HOXA9 and mut-KRAS in each tumor, but the levels varied." (PMID 33322500, 2020). "A further study found that HOXA9 was hypermethylated in 51% of tumour samples, particularly earlier stage carcinomas which were mostly of the endometriod histological subtype." (PMID 31382546, 2019). "Knockdown of HOXA9 strongly promoted tumor growth and the tumor sizes were apparently larger compared to siNC group at the end of the experimental period." (PMID 31683603, 2019). "HOXA9 has been identified as a tumor suppressor in cSCC by inhibiting glycolysis while promoting apoptosis." (PMID 31683603, 2019). "HOXA9 can function as a tumor suppressor gene though downregulation of the HIF-1α gene in cutaneous squamous cell carcinoma (cSCC)." (PMID 31013831, 2019). "This study showed that the overexpression of HOXA9 significantly enhances in vitro normal cell migration and invasion and that tumour cell migration and invasion can be inhibited by downregulating HOXA9." (PMID 31043660, 2019). "Given the essential role of HIF-1α in glucose metabolism, glycolysis is inhibited by the tumor suppressor, HOXA9." (PMID 31013831, 2019). "The HOXA9-NF-κB regulatory axis identified demonstrates how one tumor suppressor, HOXA9, negatively enhances apoptosis and suppresses autophagy through transcriptionally regulating NF-κB." (PMID 31683603, 2019). "Over-expression of HOXA9 was found to enhance alkaline phosphatase activity, mineralization, and in vitro tumour cell migration and invasion, whereas downregulation had the opposite effects." (PMID 31043660, 2019). "Further work has confirmed the importance of HOXA9, one study found the cumulative methylation score for three genes (HOXA9, RASSF1A and OPCML) was significantly associated with tumour stage, especially when combined with CA-125 level." (PMID 31382546, 2019).
tumor (continued). "HOXA9 acts as a tumor suppressor and inhibits glycolysis in cSCC in vitro and in vivo by negatively regulating HIF-1α and its downstream glycolytic regulators, HK2, GLUT1 and PDK1." (PMID 29662084, 2018). "After the 9th day, HOXA9 depletion markedly enhanced tumor growth when compared with the siNC control group." (PMID 29662084, 2018). "As HOXA9 plays a pro-carcinogenic role in blood cancer, identification of the factor that mediates the “switching” of HOXA9 as an oncogene or a tumor suppressor would be of particular value to understand and potentially treat disparate oncogenesis." (PMID 29662084, 2018). "HOXA9 regulates embryonic development and functions in different stages of various tumors, either as an oncogene or as a tumor suppressor." (PMID 29662084, 2018). "Herein, CRIP2 was identified to be a direct interacting partner of HOXA9 and acted as a tumor suppressor in cSCC, consistent with the previous-reported anti-carcinogenic role of CRIP244,45,57." (PMID 29662084, 2018). "Bioinformatics analysis of the HOXA9-depleted transcriptome in cSCC cells uncovered the new role of HOXA9 in regulating glycolytic metabolism, which is critical for the tumor-suppressive function of HOXA9 as confirmed by the subsequent validations." (PMID 29662084, 2018). "HOXA9 overexpression markedly delayed tumor growth immediately following injection when compared with the vector control." (PMID 29662084, 2018). "Using these criteria, 73 and 87% of tumor samples were considered hypermethylated at HOXA9 and OXR1 promoters, respectively." (PMID 28662726, 2017). "Compared to the adjacent non-tumor mucosal tissues, the HOXA9 expressed significantly higher in primary CRC tissues and highest in the CRC tissues with metastasis." (PMID 28969042, 2017). "In conclusion, we newly determined that miR-133b targeted the HOXA9/ZEB1 pathway to promote tumor metastasis in CRC cells." (PMID 28969042, 2017). "Six tumor-associated genes (RASSF1A, APC, BVES, TIMP3, GSTP1, and HOXA9) were selected as candidates." (PMID 28951629, 2017). "Induced levels of either TET1 or HOXA9 suppressed cell invasion in vitro and xenograph tumour growth and invasion when injected into nude mice mammary fat pads." (PMID 28587163, 2017). "Tumor samples were categorized as HOXA9 or OXR1 methylated using the respective highest methylation ratio value observed in normal/control samples as cutoff (14.11 for HOXA9 and 1577.45 for OXR1)." (PMID 28662726, 2017). "Since our findings support previous associations of HOXA9 and ISL1 methylation with tumour characteristics and behaviour, we appraised potential clinical correlates of HOXA9 and ISL1 methylation, including their prognostic potential." (PMID 26332997, 2015). "Tumor-associated angiogenesis, another critical hallmark of GBM, as assessed by PECAM1 protein staining, was significantly increased in HOXA9-positive tumors." (PMID 25762636, 2015). "We first confirmed that BCL2 is significantly overexpressed at the mRNA and protein levels in HOXA9-positive cells, which was consistent with increased levels of BCL2 protein in HOXA9-expressing subcutaneous tumor." (PMID 25762636, 2015). "Conversely, frequency of methylation was lower in HG-NMIBCs for HOXA9 (20/36; 55.6%) compared to low/intermediate-grade tumours (10/12; 83.3%, p = 0.167);." (PMID 26332997, 2015). "Histological and RT-PCR analyses confirmed tumor formation and HOXA9 expression levels in tumors excised from mice brains (respectively)." (PMID 25762636, 2015).
tumor (continued). "We next determined the correlation between gene-specific methylation with clinical outcomes within the HG tumour cohort; HOXA9 and ISL1 were assessed as the only genes demonstrating a significant difference in frequency or level of methylation." (PMID 26332997, 2015). "Concurrent ISL1/HOXA9 methylation in HG-NMIBC reliably predicted tumour recurrence and progression within one year (Positive Predictive Value 91.7%), and was associated with disease-specific mortality (DSM)." (PMID 26332997, 2015). "In our HG-NMIBC cohort, HOXA9 or ISL1 methylation at initial diagnosis reliably predicted tumour recurrence or progression within one year." (PMID 26332997, 2015). "Because the biological behavior of ascitic tumor cells markedly differs from that of solid tumors, we investigated the effect of HOXA9 on floating EOC cells in ascites." (PMID 25023983, 2014). "We previously identified that high HOXA9 expression is strongly associated with poor overall survival in EOC patients and promotes tumor progression in EOC xenograft models." (PMID 25023983, 2014). "In conclusion, this study demonstrated that low expression levels of the tumor suppressor, miR-196b, were associated with up-regulation of the oncogenes BCR-ABL1 and HOXA9, ultimately leading to the development of CML." (PMID 23894305, 2013). "In a series of 24 MCL with available CGH data, tumours with methylated SOX9 (P = 0.023) or HOXA9 (P = 0.006) showed a higher number of chromosomal abnormalities than unmethylated cases." (PMID 21603610, 2011). "MCL with methylated SOX9 (p = 0.001) or HOXA9 (P = 0.002) showed significant higher proliferation (Ki-67 index) than unmethylated tumours." (PMID 21603610, 2011). "We focused in those genes that were significantly differently methylated in the basal-like tumor subtype (HOXA9, SOX1, VAMP8, and TNFRS10D) and those that were significantly hypermethylated in the luminal B tumors (NPY, RASSF1, HS3ST2, DBC1, FGF2, CD40." (PMID 20920229, 2010). "In the present study, HOXA9 promoter methylation was more frequent in tumours from older patients than in tumours from younger patients." (PMID 17623056, 2007). "DNA hypermethylation of tumour suppressor genes seems to play an important role in ovarian carcinogenesis and HOXA9, HOXB5, SCGB3A1, and CRABP1 are identified as novel hypermethylated target genes in this tumour type." (PMID 17623056, 2007). "In addition, significant direct correlations between high H score values of HOXA9 staining and larger tumor size (p < 0.004) and older patient age (p < 0.047) were registered." (PMID 39462379, 2024). "HOXA9 was accused in tumor progression through multiple signaling pathways." (PMID 39462379, 2024). "The tumor-promoting property of HOXA9 in EOC cells is mediated through the activation of TGF-β2." (PMID 38904676, 2024). "Similarly, methylation of the HOXA9 promoter from circulating tumor DNA was successfully used to PARPi-based therapy in patients with platinum-resistant OC and germline BRCA mutations." (PMID 39588300, 2024). "Taken together, HOXA9 stimulates TAM attraction in tumors which might be involved in tumor progression." (PMID 39462379, 2024). "Also, it was implied that cancer-associated gene pathways were enriched in HOXA9, PRC2-EED, PRC2-EZH2, SNF5, VEGF-A, which exerted as a vital role in transcriptional regulation, epigenetic regulation and tumor angiogenesis." (PMID 37520979, 2023). "However, the multiple modes of regulation, multifaceted functions, and context-dependent interactions responsible for the dual role of HOXA9 as an oncogene or tumor suppressor in cancer remain obscure." (PMID 38062297, 2023). "However, further investigation into the relationship between the Wnt/β-catenin pathway and HOXA9 will be benefit for tumor treatment." (PMID 36376832, 2022).